FH (fumarate hydratase)
Diseases named in the same sentence as FH in open-access papers (continued):
Sharing a sentence is not in itself a finding about the gene and the disease.
cancer (continued). "This study provides new insights into the FH in pan-cancer and novel clues for further exploration of the mechanism of FH in cancer." (PMID 34737838, 2021). "In this study, we analyzed the expression of FH and evaluated its prognostic value in 33 cancer types." (PMID 34737838, 2021). "A growing number of studies have shown that FH is involved in the occurrence and development of certain cancers." (PMID 34737838, 2021). "Gene mutations related to the TCA cycle enzymes fumarate hydratase (FH), succinate dehydrogenase (SDH) and isocitrate dehydrogenase (IDH) were variously discovered in cancer cells." (PMID 34200553, 2021). "In conclusion, we performed a pan-cancer analysis of the FH and elucidated the prognostic and immune significance of FH expression in human cancers." (PMID 34737838, 2021). "On the other hand, fumarate hydratase (FH) and succinate dehydrogenase (SDH) genes are mutated in many human cancers, including BC, which leads to the accumulation of their substrates, fumarate and succinate, respectively." (PMID 34072826, 2021). "TCA cycle genes, encoding isocitrate dehydrogenase (IDH1 and IDH2), fumarate hydratase (FH), and succinate dehydrogenase (SDHA, SDHB, SDHC, SDHD, and SDHAF2) are mutated both germinally and somatically in a number of human cancers." (PMID 33572577, 2021). "Mutations in its three key enzymes—fumarate hydratase (FH), succinate dehydrogenase (SDH) and isocitrate dehydrogenase (IDH)—are associated with EMT and cancer progression." (PMID 33673109, 2021). "Loss-of-function mutations in the TCA cycle enzymes fumarate hydratase (FH) and succinate dehydrogenase (SDH) have been identified as driver mutations in cancer and mediators of epigenetic reprogramming." (PMID 35004688, 2021). "To further understand the roles of FH in cancer, we explored the prognostic value of FH in pan-cancer." (PMID 34737838, 2021). "In the present study, we found that FH was upregulated in 21 types of cancers tissues than in normal tissues." (PMID 34737838, 2021). "It will be interesting to investigate if FH and SDHx mutations also inhibit KDM4B and act as cooperating factors to promote ALT in ATRX-mutated cancers." (PMID 33972520, 2021). "On the other hand, we found FH was upregulated in 21 types of cancers and related to patients' poor prognosis and immunity in LUAD." (PMID 34737838, 2021). "Respiration incompetency is a feature of some of the most aggressive cancer types, such as ones carrying mutations in the TCA cycle enzymes fumarate hydratase (FH) and succinate dehydrogenase (SDH)." (PMID 34827664, 2021). "Although hyper-succinylated proteins have been already associated with the tumors with SDH, FH and IDH deficiency, the impact of this post-translational modification in cancer cells is still matter of investigation." (PMID 34065551, 2021). "FH and SDH mutations initiate retrograde mitochondrial signaling, leading to the accumulation of fumarate and succinate in the carcinoma cells due to UPRmt." (PMID 34717757, 2021). "Pseudohypoxia is observed in cancers with SDH and FH mutations and is proposed to occur due to succinate/fumarate-induced inhibition of the HIF hydroxylases." (PMID 32985654, 2020). "Mutations in genes encoding aconitase, isocitrate dehydrogenase (IDH), succinate dehydrogenase (SDH), fumarate hydratase (FH), and citrate synthase have been observed in many cancer types." (PMID 32252351, 2020). "Cancer-associated mutations in genes encoding IDH, FH, and SDH lead to the accumulation of 2-hydroxyglutarate, fumarate, and succinate, respectively." (PMID 32252351, 2020). "Several enzymes of the TCA cycle are often mutated or deregulated in human cancers, including aconitase (also known as aconitate hydratase, AH), isocitrate dehydrogenase (IDH), fumarate hydratase (FH), succinate dehydrogenase (SDH), and KGDHC." (PMID 32397535, 2020).
cancer (continued). "Succinate dehydrogenase complex iron sulfur subunit B (SDHB), fumarate hydratase (FH), and the cytosolic and mitochondrial isocitrate dehydrogenase (IDH) isoforms 1 and 2 have been shown to be mutated in various types of cancer." (PMID 32365833, 2020). "Mutations in the genes encoding Krebs cycle enzymes fumarate hydratase (FH) and succinate dehydrogenase (SDH), amongst others, are associated with cancer development." (PMID 32985654, 2020). "More importantly, cancer occurrence has been linked to genetic mutations in isocitrate dehydrogenase (IDH) 2, succinate dehydrogenase (SDH) subunits and FH." (PMID 30668541, 2019). "In view of the close relationship between the functional status of FH and epigenetic regulation, it is very meaningful to understand the specific role of FH in cancer development and progression." (PMID 31435524, 2019). "Multiple cycle enzymes, including aconitase (also known as aconitate hydratase, AH), isocitrate dehydrogenase (IDH), FH, succinate dehydrogenase (SDH) and KGDHC, are frequently mutated or deregulated in human cancers." (PMID 28748451, 2018). "Mutations in genes encoding fumarate hydratase (FH) and succinate dehydrogenase (SDH) have also been identified in many cancers." (PMID 30279699, 2018). "The metabolic enzymes fumarate hydratase (FH) and succinate dehydrogenase (SDH) are also frequently mutated in certain cancers." (PMID 29784032, 2018). "These oncometabolites are produced by mutations in the nuclear-encoded TCA enzymes, isocitrate dehydrogenase 1 and 2 (IDH1/2), succinate dehydrogenase (SDH), and fumarate hydratase (FH), and have been found in human cancers." (PMID 29342092, 2018). "Fumarate hydratase (FH) is an enzyme of the tricarboxylic acid (TCA) cycle mutated in hereditary and sporadic cancers." (PMID 29069586, 2017). "Mutations in IDH, FH, and SDH are common in cancer and these metabolites contribute to cancer growth and survival by reduced expression of tumor suppression genes." (PMID 28966808, 2017). "Epigenetic alterations play major roles in establishing and maintaining aberrant gene expression profiles in cancer cells and in particular in the hypermethylated cluster M1 involving all PPGL with SDHx and FH mutations." (PMID 28471419, 2017). "To date, the metabolic mutations associated with cancer are found mainly in isocitrate dehydrogenase (IDH), succinate dehydrogenase (SDH), and fumarate hydratase (FH)." (PMID 26812134, 2016). "The discovery that mutations in the metabolic genes Fumarate hydratase (FH), Succinate dehydrogenase (SDH) (IDH) lead to cancer further supported a primary role of metabolic alterations in tumorigenesis." (PMID 27117029, 2016). "Mutations in the mitochondrial genes for the TCA cycle 39, including succinate dehydrogenase (SDH) and fumarate hydratase (FH), are well recognized in cancer cells." (PMID 26843513, 2016). "On the one hand, a recent study showed that mutations in fumarate hydratase (FH) and succinate dehydrogenase (SDH) detected in various cancers are associated with 5hmC level." (PMID 26462176, 2015). "In contrast to ccRCC18, relatively little is known about the mutations that drive pRCC growth and the clonality of copy number events and single-nucleotide variants (SNVs), apart from the small minority of cancers with changes in MET and FH." (PMID 25790038, 2015). "For example, some cancer cells harbor mutations in TCA enzymes (e.g., FH, SDH, IDH2) or regulatory proteins that control mitophagy (i.e., LKB1)." (PMID 25621173, 2015). "The mutations in genes encoding enzymes of SDH complex and FH in TCA cycle pathway have previously been linked with mitochondrial dysfunction and cancers." (PMID 26377099, 2015). "We initially investigated all 31 cancers and paired constitutional DNA for mutations in the Mendelian pRCC genes MET, FH and FLCN." (PMID 25790038, 2015). "For example fumarate hydratase (FH) and succinate dehydrogenase (SDH) are two Krebs cycle enzymes found mutated in a variety of human cancers." (PMID 24858415, 2014).
cancer (continued). "While the relevance of FH, EXO1, MAP1LC3C and PLD5 functions to the development of cancer is plausible, that of the associated RGS7 is intriguing and deserves comments." (PMID 23555580, 2013). "The mitochondrial defects and high fumarate accumulation, as a result of fumarate hydratase dysfunction, has several important consequences for the cancer cell." (PMID 23967283, 2013). "Likewise, fumarate hydratase (FH), a critical enzyme in the tricarboxylic acid (TCA) cycle, is implicated in hereditary and sporadic cancers due to mutations." (PMID 40272602, 2025). "Notably, in human cancers caused by mutations in IDH1, FH or SDH, the accumulation of metabolites in the TCA cycle, such as succinate and fumarate, is also frequently observed." (PMID 40523311, 2025). "Our findings may provide alternative therapy strategies for cancers with mutations of the key enzymes in TCA cycle, especially FH-dRCC." (PMID 41427347, 2025). "Emerging evidence suggests that alterations in metabolic enzymes may contribute to angiogenic signaling in cancer, implicating fumarate hydratase (FH) as a potential contributor in this process." (PMID 41008787, 2025). "In addition, many cancers harbor mutations in genes related to metabolism, including those encoding enzymes such as succinate dehydrogenase (SDH), fumarate hydratase (FH), and isocitrate dehydrogenase (IDH)." (PMID 39409901, 2024). "TOMM40 and FH were associated with TMB and MSI in a range of cancers." (PMID 38285218, 2024). "The proportion of MDH2‐positive BxPC3 cells and Panc1 cells was 31% and 69%, while the proportion of FH‐positive BxPC3 cells and Panc1 cells was 57% and 88%, respectively, indicating higher energy production and altered hyperactive metabolism in cancer cells." (PMID 38483955, 2024). "Numerous cancers exhibit mutations in critical enzyme of tricarboxylic acid (TCA) cycle, including isocitrate dehydrogenase (IDH), succinate dehydrogenase (SDH), and fumarate hydratase (FH)." (PMID 39403716, 2024). "ER stress could affect crucial enzyme (MDH2 and FH) activity of metabolic cascade in cancer cells, boosting aerobic respiration and attenuating the Warburg effect to promote cell apoptosis." (PMID 38483955, 2024). "Therefore, the FH-RLR signaling pathway in TAMs emerges as a promising avenue for cancer immunotherapy, albeit necessitating further investigative endeavors to fully elucidate its therapeutic potential." (PMID 38185636, 2024). "However, recent evidence suggests that these carcinomas can occur sporadically; thus, in the 2022 WHO classification, FH-deficient RCC includes sporadic and hereditary cases." (PMID 37999735, 2024). "The loss of FH causes hypermethylation in the promoter of the tumor suppressor cyclin-dependent kinase inhibitor 2A (CDKN2A), the hypermethylation of CDKN2A is a predictive factor for unfavorable prognosis of various cancers." (PMID 36778129, 2023). "Oncometabolites, which mainly include 2-hydroxyglutarate, succinate and fumarate, refer to metabolites that drive distinct cancers and arise in human cancer due to somatic mutations in the isocitrate dehydrogenase (IDH) genes, fumarate hydratase (FH), or succinate dehydrogenase (SDH) gene." (PMID 37391812, 2023). "In cancer cells, fumaric acid can be catalyzed using fumarate hydratase to produce malic acid." (PMID 38139250, 2023). "Mutations in the genes encoding fumarate hydratase (FH), isocitrate dehydrogenase (IDH), and succinate dehydrogenase (SDH) cause TCA cycle dysfunction and mitochondrial metabolic defects in various types of cancers." (PMID 36959802, 2023).
cancer (continued). "Metabolic screening of tumors could become important, when specific therapies for metabolically dysregulated cancers with SDHx, FH, or IDH1/2 PV become available, as targeted LC-MS/MS analysis is faster and cheaper than sequencing analyses." (PMID 36897220, 2023). "Thus, mutations in TCA enzymes, such as succinate dehydrogenase (SDH) or fumarate hydratase (FH), can lead to anomalous, pseudo-hypoxic cell responses, as observed in different types of cancer." (PMID 37686461, 2023). "The net effect of ferroptosis on FH-inactivated HLRCC is still unknown, and further, more comprehensive studies are needed to determine the impact of fumarate hydratase on ferroptosis in other cancers." (PMID 37325669, 2023). "Mutations in FH and SDH in these cancer cells cause an accumulation of fumarate and succinate, respectively which ooze out of the mitochondrial matrix and inhibit the prolyl hydroxylases (PHDs), leading to apoptotic resistance and hypoxia signalling even under oxygen-stable conditions." (PMID 35382567, 2022). "Fumarate and succinate antagonize the roles of α-KG In addition to IDH1 and IDH2, germinal and somatic mutations of fumarate hydratase (FH) and succinate dehydrogenases (SDHA, SDHB, SDHC, SDHD, and SDHAF2), encoding FH and SDH enzymes, are common in a number of human cancers." (PMID 34050894, 2022). "Importantly, mutations in the tricarboxylic acid cycle enzymes succinate dehydrogenase (SDH) and fumarate hydratase (FH), which interconvert succinate and fumarate, respectively, are highly common in cancer." (PMID 35269796, 2022). "Although HLRCC tumors metastasize rapidly, FH-deficient mice develop premalignant cysts in the kidneys, rather than carcinomas." (PMID 36269833, 2022). "In addition, in cancer cells with defective FH, α-KG is concomitantly metabolized in both pathways: oxidative decarboxylation via the TCA cycle and reductive carboxylation via IDH2." (PMID 34829892, 2021). "The Kaplan-Meier curves showed that increased FH expression was correlated with poor prognosis in 6 cancer types including ACC (P = 0.00069, HR = 1.01), KICH (P < 0.0001, HR = 1.02), LAML (P < 0.0001, HR = 1.02), LGG (P < 0.0001, HR = 1), LUAD (P = 0.014, HR = 1), and SKCM (P < 0.0001, HR = 1)." (PMID 34737838, 2021). "In addition, the loss of FH and the accumulation of fumarate elicit an epithelial-to-mesenchymal-transition (EMT) to promote cancer metastasis." (PMID 34737838, 2021). "A recent study in patients with advanced RCC demonstrated the occurrence of pathogenic germline mutations in genes predisposing to cancer development in 16.1% of cases, with 5.5% carrying aberrations in syndromic RCC-associated genes, most commonly FH and SDHx." (PMID 34822422, 2021). "In addition, FH and IDH mutations lead to tumor initiation through the repression of cellular differentiation, and IDH1 and IDH2 mutations cause an energy shift in cancer cells." (PMID 34445360, 2021). "The role of mitochondria in cancer development is primarily focused on mutations in genes in TCA cycle enzymes, namely succinate dehydrogenase (SDH), fumarate hydratase (FH) and isocitrate dehydrogenase 2 (IDH2), leading to the accumulation of succinate, fumarate and 2-hydroxyglycerate (2HG)." (PMID 34829708, 2021). "We cannot rule out the possibility that the FH mutation per se can protect against cancer, but this is less plausible from a current biological point of view." (PMID 31848411, 2019). "It is indicated that, in cancer cells, mutations in TCA cycle enzymes, fumarate hydratase (FH) and succinate dehydrogenase (SDH), or complexes of the electron transfer chain (ETC), such as complex I and complex III, could promote glutamine utilization." (PMID 31611919, 2019). "Cancer cells also inhibit the mitochondrial TCA cycle through the upregulation of pyruvate dehydrogenase kinase (PDK) expression and mutations of fumarate hydratase (FH) and succinate dehydrogenase (SDH), while promoting glycolysis." (PMID 30708988, 2019).
cancer (continued). "To test this hypothesis in cancer cells, we examined the effects of ONC201 on UOK262 fumarate hydratase deficient (FH [−/−]) cells in which mitochondrial respiration is defective due to mutation of the FH gene." (PMID 29719618, 2018). "Interestingly, FH impaired or deficient cells display decreased levels of NADPH and high levels of ROS, which activate cancer metabolism." (PMID 30671168, 2018). "Interestingly, recent work highlighted the sensitivity of FH-deficient cell lines to the poly (ADP-ribose) polymerase (PARP) inhibitor, olaparib, known to affect cancers deficient in HRR10." (PMID 30190474, 2018). "Deregulated cellular energetics in cancer cells may be induced by defection of mitochondrial metabolic enzymes, including fumarate hydratase (FH), succinate dehydrogenase (SDH), and isocitrate dehydrogenase (IDH)." (PMID 30671168, 2018). "In this study, the FH expression in cancer cells with PVT was more than 2-fold decreased." (PMID 28785178, 2017). "Mutations in FH and SDH in these cancer cells cause an accumulation of metabolites which leak out of the mitochondrial matrix and inhibit prolyl hydralase (PHD) enzymes, leading to apoptotic resistance and hypoxia signaling (even under oxygen-stable conditions)." (PMID 28491867, 2017). "Unlike SDH and FH loss-of-function mutations of which have been identified in various cancers, R132 and R172 mutations in IDH1 and 2 (the neomorphic allele producing mutations); respectively, do not follow Knudson’s two-hit model of tumor suppressor genes." (PMID 28785398, 2017). "In addition, mutations in succinate dehydrogenase (SDH) and fumarate hydratase (FH), enzymes that produce competitive metabolites for PHD cofactors, are found in cancers." (PMID 27058900, 2016). "Although glutaminolysis in normal cells is known to require OGDH, cancer cells frequently have mutations in the TCA cycle enzymes succinate dehydrogenase and fumarate hydratase downstream of OGDH, and also reduce the OGDH substrate 2-oxoglutarate to 2-hydroxyglutarate." (PMID 27027236, 2016). "Interestingly, FH-null cancer cells also display hyper-activation of the master antioxidant transcription factor NRF2." (PMID 25671107, 2014). "The level of G6PDH was on average two to threefold higher in UOK262, UOK262EV and UOK268 cancer cells than in the HRCE cells, while FH restoration in UOK262WT cells caused a reduction of the G6PDH level, more closely approximating those observed in the HRCE cells." (PMID 23967283, 2013). "Growing evidence emphasizes the interplay between metabolic disturbances, epigenomic changes and cancer, i.e., mutations in the metabolic enzymes SDH, FH, and IDH may contribute to cancer development." (PMID 24202337, 2013). "We hypothesized that FH-deficient cells may be auxotrophic for arginine, a phenomenon often observed in ASS1-negative cancers." (PMID 23643539, 2013). "AKT activation is a common signaling node in cancer and alternate mechanisms may lead to AKT activation in RCC including loss of FH." (PMID 21695080, 2011). "Our findings imply that FH deficiency leads to cancer because there is not enough fumaric acid in the nucleus to stimulate repair of DNA double-strand breaks; the persistence of these breaks is believed to provoke cancer." (PMID 20231875, 2010). "One of the most important findings in this study is that FH autoantibody levels in stage I are significantly higher than in healthy subjects, but from the perspective of false positive rates, it is difficult to screen for early cancer using FH autoantibodies alone." (PMID 38791507, 2024). "However, the inhibition of FH exhibits anti-proliferative activities in a variety of cancer cells." (PMID 37592347, 2023). "However, cells are capable of proliferating without this enzyme, and moreover, mutation or deletion of FH is an apparent driver of various cancers." (PMID 36428601, 2022).